PLAGL1 (PLAG1 like zinc finger 1)
Diseases named in the same sentence as PLAGL1 in open-access papers (continued):
Sharing a sentence is not in itself a finding about the gene and the disease.
MODY (1 paper, 2022). "Therefore, we pay special attention to the four patients whose PLAGL1 is overexpressed (particularly evident in patients M8 and M15) since this trend would explain a possible association with MODY and not the opposite." (PMID 35246208, 2022).
pancreatic cancer (1 paper, 2023). "PLAGL1 overexpression and vector control plasmid were purchased from MiaolingBio (Wuhan, China), and were transfected into pancreatic cancer cells using Lipofectamine 2000 (Invitrogen, USA) following the manufacturer's instruction." (PMID 36600208, 2023). "Additionally, through MTS and BrdU assays, we further demonstrated in vitro that PLAGL1 had the impact of preventing the proliferation of pancreatic cancer cells." (PMID 36600208, 2023). "Therefore, our data indicated that PLAGL1 had the impact of preventing the proliferation of pancreatic cancer cells." (PMID 36600208, 2023). "Finally, we found a decreased proliferation rate of pancreatic cancer cells with PLAGL1 overexpression in vitro." (PMID 36600208, 2023).
pancreatic tumor (1 paper, 2023). "We also performed tissue microarray IHC staining of PLAGL1 in two other independent cohorts of PAAD and pancreatic tumor-adjacent tissues." (PMID 36600208, 2023).
Parkinson disease (1 paper, 2012). A progressive degenerative disorder of the central nervous system characterized by loss of dopamine producing neurons in the substantia nigra and the presence of Lewy bodies in the substantia nigra and locus coeruleus. "The genes in one region are known to be involved in imprinting in human and mouse placenta (region Ger1 - Zac/Plagl1) and include a further gene suspected to be a risk factor in Parkinson's disease (Phactr2)." (PMID 22956910, 2012).
pheochromocytoma (1 paper, 2013). "PLAGL1 is thought to be a transcriptional regulator and has been associated with pheochromocytoma, a tumor of the adrenal grand." (PMID 23890537, 2013).
pregnancy diseases (1 paper, 2020). "By combining computational predictions with experimental validations, we were able to identify novel functions for PLAGL1 in two models frequently used to study human placenta, which could contribute to insights into placental development and certain pregnancy disorders." (PMID 33171905, 2020). "Therefore, PLAGL1 may be an interesting target of analysis when understanding the pathogenesis of pregnancy diseases." (PMID 33171905, 2020).
sarcoma (1 paper, 2013). A usually aggressive malignant neoplasm of the soft tissue or bone. "The aims of this study were to evaluate the importance of individual PLAGL1 promoter P1 CpG sites for PLAGL1 mRNA expression and their potential association with sarcoma patient outcomes." (PMID 24260468, 2013). "PLAGL1 is a maternally-imprinted gene, which maps to the human chromosome 6q24.2, a region often rearranged in many cancers, including sarcomas." (PMID 24260468, 2013).
Sepsis (1 paper, 2023). Sepsis is defined as life-threatening organ dysfunction caused by a dysregulated host response to infection. "Under sepsis condition, differentially overexpressed CNTLN, ICAM1, and PLAGL1 in PTB were consistently observed." (PMID 36788602, 2023).
Temple syndrome (1 paper, 2017). "In addition to the differentially methylated regions on chromosomes 7, 11, and 14 which are affected in the imprinting disorders SRS and Temple syndrome, imprinted loci (PLAGL1, IGF2R) on chromosome 6 were investigated in all these cases as well." (PMID 29178649, 2017).
viral infection (1 paper, 2024). "The functional enrichment analysis showed PLAGL1 overexpression induced differential expression genes enriched in the inflammatory response similar to a viral infection." (PMID 39365284, 2024).
tumor (47 papers, 2006 to 2026). "Being an imprinted gene, PLAGL1 is widely expressed across human organs from embryo to adult stages, and its aberrant expression has been linked to various human tumours." (PMID 39365284, 2024). "One of the PLAGL1 transcripts (ZAC1) encodes a protein that inhibits tumor-cell-proliferation through the induction of cell cycle arrest and apoptosis." (PMID 35764919, 2022). "The loss or reduction of LOT1/ZAC1/PLAGL1 expression in several types of cancers and its proapoptotic and cell cycle arresting properties have suggested its potential role as a tumor suppressor." (PMID 33918057, 2021). "Loss of PLAGL1 expression is frequently observed in many human tumours, consistent with its proposed role as a tumour-suppressor gene." (PMID 22723905, 2012). "In addition, multiple cell lines from several tumor categories showed PLAGL1 copy number loss or the loss of expression of its multiple isoforms in our dataset." (PMID 40414875, 2025). "Our in silico analyses demonstrated that neoplasm-related mortality might be due to the removal of TFBS for PLAGL1 zinc finger 1 protein, which is associated with anti-proliferative activities and tumour suppression." (PMID 33482747, 2021). "This function aligns with Plagl1's broader tumor suppressor role in stabilizing postmitotic, differentiated cell states across tissues." (PMID 41849358, 2026). "In one tumor with PLAGL1 amplification (#A388), we found separate focal high-level amplification of the GLI2 oncogene on chromosome 2q14.2, and in another tumor with PLAGL1 amplification (#A93), we found focal amplification of MYB on chromosome 6q23.3." (PMID 36437415, 2023). "IGs are considered to be key regulators of embryonic development and global loss of imprinting (LOI) as well as LOI of IGF2, which is regulated by PLAGL1, can lead to tumor formation." (PMID 36437415, 2023). "Gene expression profiles of 11 tumors with amplification of PLAGL1 (n = 5) or PLAGL2 (n = 6) were compared to gene expression profiles of a total of 279 tumor samples from various other CNS tumor types and normal tissues." (PMID 36437415, 2023). "While PLAGL1 has been suggested as a putative tumor suppressor gene, PLAG1 and PLAGL2 are presumed proto-oncogenes." (PMID 36437415, 2023). "Suppression of PLAGL1 expression during tumor metastasis has been proposed to be related to transcriptional repression through the recruitment of methyltransferase and aberrant DNA methylation in the promoter region." (PMID 33918057, 2021). "PLAGL1 expression has also been found to be increased in some tumor tissues, and decreased in others." (PMID 33171905, 2020). "Reduced transcription of PLAGL1 is common to several tumor types, but the results of protein expression are intriguing." (PMID 30214684, 2018). "The tumor cell-lines showed a rather uniform expression level of PLAGL1 during the growth assays, except for SkHep1 cells that presented significant lower expression levels at 48 and 96 h of the experiment." (PMID 30214684, 2018). "To study the effect of PLAGL1 overexpression on HCC cells proliferation, we performed transfection assays in two tumor cell-lines (PLC/PRF/5 and HepG2) with a plasmid encoding the full-length protein." (PMID 30214684, 2018). "Regarding the region 6q24.2, the log-ratios for Huh7 and SKHep1 cells were −1.368 and −0.582, respectively, indicating that both tumor cell lines presented losses at the locus of PLAGL1 gene." (PMID 30214684, 2018).
tumor (continued). "PLAGL1 immunoreactivity was weakly detected in the cytoplasm of tumor cells, while in normal fibroblasts its expression was readily observed in the nucleus and the cytoplasm." (PMID 30214684, 2018). "The microscopic analysis revealed that, except for two (H004 and H011), all tumor samples had lower expression of PLAGL1 protein than normal liver cells." (PMID 30214684, 2018). "There is evidence that PLAGL1 acts as a tumour suppressor in many tissues, as down-regulation has been observed in a range of different tumours, through hypermethylation of the imprinted promoter, chromosomal deletion or loss of heterozygosity." (PMID 28957425, 2017). "PLAGL1 regulates growth, and it can be considered to be a tumor-suppressor gene that regulates cell-cycle arrest and apoptosis." (PMID 25253444, 2014). "Our aim was to determine the methylation status of the 118 CpG sites in the PLAGL1 tumor-suppressor gene P1 CpG island promoter and study the potential prognostic impact of PLAGL1 promoter methylation CpG sites in STS." (PMID 24260468, 2013). "In contrast, the screening analysis of the association between each CpG site's methylation value and clinical outcomes, followed by univariate Cox analyses, revealed that PLAGL1 promoter methylation was a tumor type-specific biomarker." (PMID 24260468, 2013). "Together, these data suggest that the role of PLAGL1 in US is more consistent with the phenotype of an oncogenic than a tumor-suppressor gene." (PMID 24260468, 2013). "PLAGL1 is a zinc finger DNA binding protein with tumor suppressor activity, and overexpression of this gene has been shown to arrest β cell division and induce apoptosis." (PMID 22781086, 2012). "Notably, Plagl1 has been shown to have inhibitory effects on cell proliferation and act as a tumor suppressor in humans." (PMID 39960664, 2025). "While each PLAGL1 isoform with established allelic expression was either monoallelically or biallelically expressed within each of these tumor histologies, 18 isoforms had both monoallelic and biallelic expression patterns across all tumor categories combined." (PMID 40414875, 2025). "The tumor’s morphology may incite neuropathologists to suggest this diagnosis and search for PLAGL1 alteration by RNAseq and /or FISH analysis." (PMID 38581034, 2024). "PLAGL1 is hypothesized to act as a tumour suppressor by triggering cell cycle arrest and apoptosis through its interactions with partner proteins." (PMID 39365284, 2024). "While areas of the PLAGL1 amplified tumor showed strong positivity for GFAP or synaptophysin, sometimes with overlapping areas of staining, other areas of the tumor were largely negative for both lineage markers with small clusters or occasional cells showing positivity." (PMID 39228008, 2024). "Taken together, the results suggested that PLAGL1 might work as a tumor suppressor gene regulating tumor growth and cell proliferation in PAAD." (PMID 36600208, 2023). "The role of PLAGL1 is less clear, and it may potentially act as both tumor suppressor and oncogene depending on the context." (PMID 36437415, 2023). "This growth promotion might be accomplished through the imprinted gene networks although PLAGL1 was first discovered with its proapoptotic and antiproliferative molecular properties and regarded as a tumor suppressor gene." (PMID 33918057, 2021). "PLAGL1 showed its preferential expression in the tumor core-derived lesions." (PMID 33392508, 2020). "Simultaneously we investigated whether this overexpression of PLAGL1 protein affects proliferation of tumor cells, by determining the number of cells for each experimental condition after 30 hs post-transfection." (PMID 30214684, 2018).
tumor (continued). "Thus the silmilar protein level between these two cell types is perhaps the result of less pronounced nucleolar retention of PLAGL1 transcripts in tumor cells than in normal fibroblasts." (PMID 30214684, 2018). "Among the tumor cell-lines, only SKHep1 cells exhibited a transcriptional profile similar to that of fibroblasts, i.e., a significant reduction of the PLAGL1 mRNA level until T = 72 h and then increased to levels statistically not different to that obtained at T = 0 h." (PMID 30214684, 2018). "Therefore, we conclude that PLAGL1 amplification and subsequent overexpression may contribute to tumor formation depending on the cell of origin and developmental state." (PMID 36437415, 2023). "Finally, the oncogenic RET kinase as well as CYP2W1 are direct PLAGL1/2 targets and may be potential drug targets in this tumor type, which should be top priorities for future functional validation." (PMID 36437415, 2023). "Finally, as another example, Plagl1 (pleiomorphic adenoma gene-like 1), which is another tumor suppressor inhibiting proliferation, was hypomethylated and had higher transcript levels in CONV-R mice, again supporting increased IEC proliferation in the presence of a microbiota." (PMID 29653584, 2018). "For example, the tumor-driving H3.3K27M mutation in pediatric diffuse intrinsic pontine gliomas (DIPGs) results in the inactivation of the PRC2 complex, causing ectopic expression of LIN28B, PLAG1, and PLAGL1, and leading to the de-differentiation and hyperproliferation of tumor cells." (PMID 27588417, 2016). "The PLAGL1- and PLAGL2-amplified tumors formed separate sub-clusters within the same overarching tumor type—ET, PLAGL." (PMID 40751809, 2025). "high PLP2+ Tumor EPCs score group highly expressed ATF6, ELF1, ERG and PLAGL1 genes, while low PLP2+ Tumor EPCs score group highly expressed ATF5, TBX21, SPIB, LHX2 and JUND genes." (PMID 38482016, 2024). "It was found that ATT6, ERG and PLAGL1 were more expressed in high PLP2+ Tumor EPCs score group, while SPIB was more expressed in low PLP2+ Tumor EPCs score group (P < 0.001)." (PMID 38482016, 2024). "We describe a novel, biologically distinct type of CNS embryonal tumor—ET, PLAGL—that is presumably driven by amplification and subsequent overexpression of PLAGL1 or PLAGL2, the only recurrent molecular event detected in these tumors." (PMID 36437415, 2023). "Altered expression of both Plagl1 and Hymai were described as indicative of disease condition such as TNDM and tumours." (PMID 36751888, 2023). "Indeed, the chromosome alterations affecting the H19, KCNQ1OT1, PLAGL1 and GNAS DMRs also affected one or more WT driver genes in all analyzed cases, and the chromosome variants affecting the MEST, GRB10 and MEG3 DMRs also affected tumor driver genes in at least 83% of cases." (PMID 33217932, 2020). "Obviously, caution is warranted when interpreting these findings, but them suggest that abrogation of PLAGL1 function plays a role in HCC cells proliferation, like in other tumor types." (PMID 30214684, 2018). "All five of the identified genes (DLK1, PLAGL1, SLC22A18, TP73, and WT1) have presumed tumor suppressing functions and taken together demonstrate a strong tendency towards higher methylation at the CpG sites assessed." (PMID 23890537, 2013). "Surprisingly, that study also showed that let-7 represses several tumour suppressor genes (BRCA1, BRCA2, FANCD2, and PLAGL1, among others) and checkpoint regulators (CHEK1, BUB1, BUB1B, MAD2L1, and CDC23, among others)." (PMID 20179807, 2010). "Although the CN profiling did not reveal focal alterations involving PLAGL1, the tumour had some focal and small CNAs across chromosomes, highlighted in red circles." (PMID 41033792, 2025). "In addition, we also analyzed the survival of genes which constituted PLP2+ Tumor EPCs score, and the results showed that only four of them (SPIB, ATF6, PLAGL1, ERG) were statistically significant (P<0.05)." (PMID 38482016, 2024).
tumor (continued). "This study revealed the function of PLAGL1 in reducing PAAD progression and its previously unrecognized prognostic value, providing new insight into the tumor biology of PAAD and providing us with a novel prognostic marker and therapeutic strategy that warrant investigation." (PMID 36600208, 2023). "Further molecular analyses will reveal whether any of the known tumor suppressors in this region, e.g., LATS1, PARK2, or PLAGL1, is the target of these deletions in ACC." (PMID 35954356, 2022). "Regarding the molecular mechanism, our data indicated the significance of targeting PLAGL1 to attenuate, yet not completely eliminate, tumor initiation and propagation, accompanied by an impact on survival of tumor-bearing mice." (PMID 33392508, 2020). "Statistics confirmed that PLAGL1 transcript level of tumor cells was significantly lower than that of non-tumor cells (p < 0.05)." (PMID 30214684, 2018). "Despite high variability in PLAGL1 expression was seen, the statistical analysis demonstrated that there were not significant differences in the expression level of PLAGL1 between tumor cells and fibroblasts." (PMID 30214684, 2018). "Additionally, 7 genes known to possess tumor suppressor function (e.g. GPC3/OCI-5, LOT1/PLAGL1/ZAC1, etc) were down-regulated by MEK-activation." (PMID 17112382, 2006). "One possibility is that amplification of PLAGL2 leading to tumor formation can only occur during a small spatiotemporal window during development when PLAGL2 is expressed, while amplification of PLAGL1 might be less temporally limited in terms of subsequent tumor formation." (PMID 36437415, 2023). "Furthermore, it is also known that tumor suppressor levels of PLAGL1 decline in the absence of functional AIP, but the mechanism leading to this is poorly understood." (PMID 23300914, 2012). "It has also been proposed that PLAGL1 protein levels in CCRCC tissues are positively correlated with distant metastasis and worse patient prognosis; the ACAT2 gene was related to lipid metabolism, and its downregulation could lead to a poor tumor-specific survival prognosis." (PMID 38730456, 2024).